ICAM1 (intercellular adhesion molecule 1)
Diseases named in the same sentence as ICAM1 in open-access papers (continued):
Sharing a sentence is not in itself a finding about the gene and the disease.
atherosclerosis (continued). "This increase in VCAM-1 and ICAM-1 expression, mainly induced by proinflammatory cytokines or lipopolysaccharide (LPS), promotes leukocyte recruitment, adhesion, and transmigration into inflamed tissues and ultimately atherosclerosis." (PMID 37830604, 2023). "ICAM-1 and VCAM-1 have been associated with atherosclerosis and CVD risk even in HIV(-) population." (PMID 36930649, 2023). "Serum proteomics research results show that AR may act on IL-6, TNF-α, VCAM-1, MCP-1, and ICAM-1, and play anti-atherosclerosis and neuroprotective roles." (PMID 37361203, 2023). "Other observations support a role for ICAM-1 in atherosclerosis." (PMID 37237555, 2023). "In addition, VCAM-1 and ICAM-1 RNA levels are decreased, indicating that extracellular ATP induces vascular inflammation and atherosclerosis by activating P2Y2 receptor." (PMID 34981330, 2023). "In the early stages of atherosclerosis there is damage of the endothelium and activation of inflammatory mediators, which include monocyte chemoattractant protein-1, IL-8 and adhesion molecules ICAM-1, VCAM-1 and E-selectin." (PMID 36672663, 2023). "Furthermore, NF-kB induces the upregulation of several angiocrine factors, such as interleukin(IL)-6 and intercellular adhesion molecule 1 (ICAM-1), that are strictly related to an endothelial dysfunction outcome and atherosclerosis development." (PMID 36982880, 2023). "However, experiments using VCAM-1 and ICAM-1 knockout mice have reported that VCAM-1 plays a major function compared to ICAM-1 in the early stage of atherosclerosis." (PMID 37998401, 2023). "ICAM-1 is also considered as a marker of pre-clinical atherosclerosis." (PMID 36293483, 2022). "Furthermore, ICAM‐1 and VCAM‐1 are involved in the all stage of atherosclerosis, an important risk factor in pathology of AIS." (PMID 35353946, 2022). "ICAM-1 of ECs plays a pivotal role in the early phase of atherosclerosis." (PMID 36232471, 2022). "Additionally, the inflammatory biomarker, ICAM-1, is also an effective signal for atherosclerosis screening." (PMID 35817770, 2022). "Genetic elements are of importance for the elevated risk of atherosclerosis and many genes have been implicated in the initiation and progression of atherosclerosis, including integrin beta 4 (ITGB4), intercellular adhesion molecule-1 (ICAM-1), and natriuretic peptide receptor 1 (NPR1)." (PMID 36293483, 2022). "Similarly, S1P by activating S1PR3 can also promote the development of atherosclerosis, as does S1PR1 by activating endothelial ICAM-1 and VCAM-1 and causing its dysfunction." (PMID 36119733, 2022). "Moreover, the activation of YAP/TAZ in HUVECs induced a significant increase in the expression of molecules related to the occurrence and development of atherosclerosis, such as ICAM-1 and von Willebrand factor." (PMID 35935626, 2022). "However, in atherosclerosis, as well as in TNFα-induced brain injury in murine models, the importance of Vcam-1 activation was much more substantial than that of Icam-1." (PMID 35177109, 2022). "ICAM-1 plays an important role in immune and inflammatory responses, including atherosclerosis." (PMID 36035922, 2022). "DEHP promoted atherosclerosis in mice model and may enhance the expression of inflammatory mediators such as ICAM-1 and IL-8 in HUVECs via ERK and p38 MAPK signaling pathway." (PMID 35469164, 2022). "It was shown that targeting MCP-1 and ICAM-1 slows the progression of atherosclerosis." (PMID 35806463, 2022). "The activated ECs at the sites of inceptive atherosclerosis up-regulate the expression of P-selectin, intercellular adhesion molecule-1 (ICAM-1) and vascular cell adhesion molecule-1 (VCAM-1), which are critical for attracting inflammatory cells, such as monocytes, for trans-endothelial recruitment." (PMID 36304814, 2022). "Furthermore, in ApoE knockout mice, deletion of the ICAM-1 gene resulted in a marked reduction in the recruitment of monocytes to atherosclerotic lesions and was protective against atherosclerosis." (PMID 35991897, 2022).
atherosclerosis (continued). "ICAM-1, a member of the immunoglobulin superfamily, is also involved in atherogenesis, presumably through the regulation of monocyte recruitment into areas prone to atherosclerosis." (PMID 36358491, 2022). "The IL-33-mediated inhibition of atherosclerosis-associated genes, like MCP-1 and ICAM-1 (intercellular adhesion molecule 1), was also reported in the macrophages, and this anti-atherogenic action of IL-33 involved various signaling pathways, i.e., p38α, ERK1/2, JNK1/2, PI3Kγ, and NF-κB." (PMID 36552551, 2022). "Another component that modulates TNFα-induced remodeling is the erythropoietin-producing human hepatocellular receptor (EphA), which is a receptor tyrosine kinase that mediates cell-adhesion and leukocyte homing in atherosclerosis by promoting ICAM1 and VCAM1 expression on ECs." (PMID 35600479, 2022). "MANTIS appears to further impede atherosclerosis development by limiting pro-inflammatory intercellular adhesion molecule 1 (ICAM-1)-mediated endothelial monocyte adhesion by diminishing binding of BRG1 at the ICAM-1 promoter to repress its transcription." (PMID 34698214, 2021). "Besides, METTL14 interacted with FOXO1 and acted directly on the promoter regions of VCAM-1 and ICAM-1, which enhanced monocyte binding to endothelial cells during atherosclerosis." (PMID 34869371, 2021). "ICAM-1 is a leukocyte adhesion molecule that is expressed by endothelial cells in altered shear stress, inflammation, and pathophysiological conditions such as hyperplasia and atherosclerosis." (PMID 34257375, 2021). "Blood levels of ICAM-1 are elevated during progression of atherosclerosis." (PMID 33797274, 2021). "This suggested that the LDL-oxLDL-LPC axis may regulate ICAM-1/VCAM-1 expression in the context of atherosclerosis." (PMID 34346841, 2021). "Also, Icam1−/−Apoe−/− mice were shown to have significantly reduced atherosclerotic lesions, and soluble levels of ICAM-1 paralleled atherosclerosis progression in Apoe−/− mice with significantly elevated plasma concentrations compared to experiment onset." (PMID 35087886, 2021). "In addition, plasma levels of intercellular adhesion molecule-1 (ICAM-1) and E-selectin have been demonstrated as molecular markers for atherosclerosis and the development of coronary heart disease." (PMID 34191823, 2021). "Interestingly, kaempferol treatment in atherosclerosis rabbits displayed a remarkable reduction in both the gene and protein expression of ICAM-1, VCAM-1." (PMID 34259096, 2021). "An increase in the contentof ICAM-1, VCAM-1, and E-selectin on the surface ofendothelial cells and in plasma is associated with the risk ofcoronary heart disease, atherosclerosis(Galkina, Ley, 2007), and pulmonary hypertension." (PMID 33659786, 2020). "Dysfunction of the endothelial cells is an important contributor to the pathobiology of atherosclerosis, and the increased secretion of adhesion molecule such as ICAM-1 and VCAM-1 in endothelial cells facilitates the macrophage adhesion to endothelial cells (Gimbrone and García-Cardeña, 2016)." (PMID 33442380, 2020). "Further, the role of ICAM-1 in early atherosclerosis is still debated, and our data suggests this HM-ICAM-1 may be important in later stages of the disease." (PMID 32208424, 2020). "Endothelial adhesion molecules such as VCAM-1, ICAM-1, E-selectin, and P-selectin are proinflammatory proteins which play a critical role in the adhesion of leukocytes to endothelial cells during the early stages of atherosclerosis." (PMID 31840162, 2020). "ICAM-1 expression in early atherosclerosis has been studied, and in some cases has been found to be minimal in earlier stages of the disease, which may explain the lack of detection in our methods." (PMID 32208424, 2020).
atherosclerosis (continued). "Coal-derived PM2.5 exacerbated the formation of atherosclerosis in mice, increased the expression levels of atherosclerosis-related proteins (ET-1, ICAM-1 and E-selectinin) in mice serum and promoted the phosphorylation of proteins relevant to MAPK signaling pathway." (PMID 32384920, 2020). "In this regard, the inflammatory mediators are activated by nuclear factor κB (NF-κB) signaling and regulates the expansion of endothelial cells via increasing the expression of ICAM-1, resulting in the relocation of leukocytes and inducing the progression of atherosclerosis." (PMID 32893859, 2020). "In this study, using the proximity ligation assay, we assessed the relative formation of high mannose, hybrid and complex α-2,6-sialyated N-glycoforms of ICAM-1 in human and mouse models of atherosclerosis, as well as in arteriovenous fistulas (AVF) of patients on hemodialysis." (PMID 32208424, 2020). "In addition, both naive and oxidized LDL increase ICAM‐1 expression in damaged blood vessels and promote atherosclerosis." (PMID 31157518, 2019). "A common genetic polymorphism rs5498 at position 1548 in codon 469 in exon 6 of the ICAM-1 gene, resulting in the substitution of lysine to glutamate (K469E), might have possible functional value in the etiology of atherosclerosis." (PMID 30674642, 2019). "YAP located in the nucleus under DF promotes endothelial cell ICAM1 and VCAM1 expression for monocyte adherence, which is correlated with key pathogenic events in atherosclerosis such as endothelial thickening and the recruitment of monocytes, which eventually turn into plaques." (PMID 31730006, 2019). "Furthermore, ICAM-1 are engaged in the development of atherosclerosis, and play an important role in stabilizing cell-cell interactions." (PMID 31905674, 2019). "Interestingly, hCB-ECs intrinsically have a lower production of the VCAM-1 and ICAM-1 which correlates to reduced recruitment of leucocytes/macrophages and thus a reduced probability of graft intimal hyperplasia and atherosclerosis in vivo." (PMID 30720769, 2019). "The intercellular adhesion molecule‐1 (ICAM‐1)/leukocyte function associated antigen‐1 (LFA‐1) adhesion system regulates leukocyte interactions, migration, and adhesion, and appears to play an important role in atherosclerosis and thrombosis." (PMID 31157518, 2019). "ICAM-1 downregulation, instead, can be justified by its limited role in the very early stages of disease, which become more important in following phases of atherosclerosis." (PMID 30356351, 2018). "However, miR-296-3p has the potential to inhibit atherosclerosis by regulating adhesion molecules, including ICAM-1 and CX3CR1." (PMID 30134788, 2018). "ICAM-1 stimulates the recruitment and firm adhesion of inflammatory cells to endothelial cells, which could promote inflammatory reactions in atherosclerosis." (PMID 28259164, 2017). "Tumor necrosis factor-alpha may play a direct role in the development of atherosclerosis through induction of ICAM-1, MCP-1, P-selectin, and E-selectin in endothelial and vascular smooth muscle cells resulting in endothelial cell apoptosis." (PMID 29187850, 2017). "Actually, ICAM-1 contributes to vascular inflammation and early atherosclerosis." (PMID 28069066, 2017). "The increase of vascular adhesion, observed by us in rabbits fed with Met excess, is consequent to the expression and production of adhesion molecules by endothelial cells, such as VCAM-1, E-selectin, and ICAM-1, the latter indicating the advanced stage of atherosclerosis." (PMID 28133545, 2017). "ICAM1 is an adhesive molecule of the immunoglobulin superfamily that is regulated by the proinflammatory cytokines and plays a crucial role in the development and progression of atherosclerosis." (PMID 28095483, 2017).
atherosclerosis (continued). "Specifically, Kanikarla-Marie and Jain showed that these 2 ketone bodies upregulate NADPH oxidase and thus cause, at the endothelial level, an increase in oxidative stress, ICAM-1 expression, and monocyte adhesion, all of which are involved in atherosclerosis development." (PMID 28535803, 2017). "In this study, we investigated the effects of DISGT on atherosclerosis-related markers, including intercellular adhesion molecule-1 (ICAM-1), vascular cell adhesion molecule-1 (VCAM-1), and E-selectin, in high-fat diet (HFD)-induced apolipoprotein E-deficient (ApoE−/−) mice." (PMID 27608856, 2016). "Furthermore, levels of mRNA of several cytokines and other mediators of atherosclerosis were largely unchanged in mice treated with ampicillin, except for reductions in aortic Ccl2 and Icam1 mRNA levels." (PMID 26799618, 2016). "The expression of VCAM-1, ICAM-1, and p-selectin plays a role in triggering the inflammatory process and has been indicated as a possible link of a low-grade chronic inflammatory process to atherosclerosis and various endocrine disorders." (PMID 27478508, 2016). "Several studies support the hypothesis that the ICAM 1 might influence the development of atherosclerosis." (PMID 27090396, 2016). "Circulating endothelial activation molecules (vascular cell adhesion molecule-1 (VCAM-1), intercellular adhesion molecule-1 (ICAM-1), E-selectin, and P-selectin), and carotid intima-media thickness (cIMT), were measured as parameters of vascular endothelial dysfunction and early atherosclerosis." (PMID 27941821, 2016). "Its activity has been associated with atherosclerosis.Additionally, NF-κB regulates the expression of a number of genes involved in celladhesion and inflammation including IL-6, TNF-α, E-selectin, vascular cell adhesionmolecule-1, ICAM-1, and L-selectin." (PMID 26397969, 2015). "Endothelial ICAM-1 expression is known to be elevated at inflammatory cell infiltration sites of atherosclerotic plaques, and ICAM-1 has been implicated in promoting atherogenesis in mouse models of atherosclerosis." (PMID 26717516, 2015). "As we found that miR-222 selectively inhibits endothelial ICAM-1 expression, which contributes to vascular inflammation and atherosclerosis, we finally explored whether miR-222 levels are altered in patients with CAD (CAD)." (PMID 26081516, 2015). "ICAM-1 and VCAM-1 modify the process underlying the adhesion between endothelial cells and monocytes, which leads mononuclear cells into artery intima and results in the early lesions of atherosclerosis." (PMID 25933220, 2015). "We found that the fine particles obviously induced both mRNA and protein expression of VCAM-1 and ICAM-1 in HUVECs, which may contribute to PM-accelerated atherosclerosis." (PMID 24987196, 2014). "However, we found that several risk factors of atherosclerosis, such as the level of TG, APOA and APOB, had a relationship with the polymorphisms of ICAM-1 in coronary atherosclerosis cases." (PMID 25310099, 2014). "ICAM-1 is an adhesion molecule which stimulates firm adhesion of leukocytes to the vascular endothelium and plays a critical role in the pathology of numerous proinflammatory vascular diseases, including atherosclerosis." (PMID 23690990, 2013). "However, the most important adhesion molecules involved in atherosclerosis appear to be intercellular cell adhesion molecule-1 (ICAM-1), endothelial cell selectin (E-selectin), and vascular cell adhesion molecule-1 (VCAM-1)." (PMID 24129228, 2013). "Indeed, VCAM-1 plays a more important role than intracellular adhesion molecule (ICAM-1) in the early progression of atherosclerosis." (PMID 23573162, 2013). "Furthermore, remnant lipoproteins directly promote the initial stages of atherosclerosis through regulating the expression of ICAM-1 and VCAM-1, which are required for attachment of monocytes to the endothelial wall." (PMID 23621905, 2013).
atherosclerosis (continued). "Although MR activation in ECs likely contributes to atherosclerosis by upregulating expression of intracellular adhesion molecule 1 (ICAM1), thereby enhancing leukocyte‐EC adhesion, much less is known about the role of SMCs during early atherosclerosis development." (PMID 23525413, 2013). "At 40 weeks, a more chronic stage of atherosclerosis, ICAM-1 levels remained at about 80% of control, but MOMA-2 and NFκB levels in treated animals dropped to 34% and 28% of control, that is, inhibition of these markers became similar to the inhibition of superoxide anion." (PMID 22811752, 2012). "We also speculate that the other components, except GroEL1 from C. pneumoniae, may contribute to the ICAM-1 expression in endothelial cells resulting in atherosclerosis." (PMID 22900050, 2012). "Similarly, in a rabbit model of atherosclerosis, supplementation with jaboticaba (P. cauliflora) peel decreased plasma levels of IL-1β, IL-6, and soluble intercellular adhesion molecule-1 (sICAM-1) and soluble vascular cell adhesion molecule-1 (sVCAM-1) and reduced atherosclerotic lesions." (PMID 41375968, 2025). "Thus, the anti-inflammatory effect of KLEPTOSE® CRYSMEB observed in vivo during the atherosclerosis process could be counterbalanced by this effect on ICAM-1." (PMID 39273695, 2024). "In terms of immune/inflammation, we found that 13 absorbed constituents including salvianolic acids A, B, and C; rosaminic acid; tanshinone IIA; and cryptotanshinone could inhibit the adhesion and migration of monocytes in atherosclerosis by regulating adhesion molecules such as ICAM1 and VCAM1." (PMID 38794213, 2024). "DEHP not only promoted atherosclerosis in mice model, study from in vitro also found that it may enhance inflammatory mediator expressions such as ICAM-1 and IL-8 in HUVECs via ERK and p38 MAPK signaling pathway, which increases the likelihood of allergic inflammatory reaction admissions." (PMID 35469164, 2022). "Finally, previous studies found that statins inhibit the expression of adhesion molecules such as vascular cell adhesion molecule-1 (VCAM-1) and intercellular cell adhesion molecule-1 (ICAM-1) in vascular endothelial cells, preventing atherosclerosis progression." (PMID 35328466, 2022). "As the major mRNA m5C methyltransferase, NSun2 upregulates the expression of ICAM-1 by methylating ICAM-1 mRNA, thereby increasing the adhesion of leukocytes to endothelial cells and contributing to the development of vascular endothelial inflammation and atherosclerosis." (PMID 36093141, 2022). "Thus, ICAM-1 can play a major role in the development of atherosclerosis and ICM." (PMID 36440000, 2022). "In addition, HDL inhibits endothelial cell adhesion molecules, including vascular cell adhesion molecule 1 (VCAM-1), intercellular adhesion molecule-1 (ICAM-1) and E-selectin, which are responsible for the binding of monocytes at sites of developing atherosclerosis." (PMID 34064071, 2021). "Interestingly, a case study of a HMOX1-deficient patient demonstrated that the absence of the enzyme triggered endothelial damage, high plasma levels of von Willebrand factor, increased ICAM-1 expression, coagulation and fibrinolysis defects, generalized inflammation and premature atherosclerosis." (PMID 32611348, 2020).